HERC2 (HECT and RLD domain containing E3 ubiquitin protein ligase 2)
Description:
E3 ubiquitin-protein ligase that regulates ubiquitin-dependent retention of repair proteins on damaged chromosomes. Recruited to sites of DNA damage in response to ionizing radiation (IR) and facilitates the assembly of UBE2N and RNF8 promoting DNA damage-induced formation of 'Lys-63'-linked ubiquitin chains. Acts as a mediator of binding specificity between UBE2N and RNF8. Involved in the maintenance of RNF168 levels. E3 ubiquitin-protein ligase that promotes the ubiquitination and proteasomal degradation of XPA which influences the circadian oscillation of DNA excision repair activity. By controlling the steady-state expression of the IGF1R receptor, indirectly regulates the insulin-like growth factor receptor signaling pathway. Also modulates iron metabolism by regulating the basal turnover of FBXL5.
Synonyms: jdf2; p528; D15F37S1; MRT38; SHEP1
Tractability: Antibody: its Gene Ontology location is reachable by antibodies, with high confidence. PROTAC: UniProt records ubiquitination sites on it; ubiquitination databases record sites on it; its protein half-life has been measured.
Gene: Protein-coding gene on chromosome 15 (28,111,040 to 28,322,179, reverse strand). Ensembl gene ENSG00000128731.
Subcellular location: Cytoplasm; Cytoplasm, cytoskeleton, microtubule organizing center, centrosome, centriole; Nucleus
Subcellular location (Human Protein Atlas): Cytosol; Plasma membrane
Pathways (Reactome):
DNA Repair: Nonhomologous End-Joining (NHEJ); Processing of DNA double-strand break ends; Recruitment and ATM-mediated phosphorylation of repair and signaling proteins at DNA double strand breaks
Cell Cycle: G2/M DNA damage checkpoint
Immune System: Antigen processing: Ubiquitination & Proteasome degradation
Metabolism of proteins: SUMOylation of DNA damage response and repair proteins
Gene Ontology:
Molecular function: protein binding; SUMO binding; ubiquitin protein ligase activity; ubiquitin protein ligase binding; guanyl-nucleotide exchange factor activity; metal ion binding; ubiquitin-protein transferase activity; zinc ion binding
Biological process: DNA damage response; protein stabilization; protein ubiquitination; intracellular protein transport; proteasome-mediated ubiquitin-dependent protein catabolic process
Cellular component: cytoplasm; cytosol; membrane; nucleus; nucleoplasm; centriole
Genetic constraint (gnomAD): Loss-of-function variants: 87 observed, 428.11 expected, observed/expected ratio (o/e) 0.2, 90% interval 0.17 to 0.24. The upper end of that interval is the gene's LOEUF score, 0.24, which puts it in group 1 of 6, group 1 being the genes least tolerant of losing a copy. Missense variants: 3,737 observed, 5,298.7 expected, observed/expected ratio (o/e) 0.71, 90% interval 0.69 to 0.73. Synonymous variants: 2,011 observed, 2,117.6 expected, observed/expected ratio (o/e) 0.95, 90% interval 0.92 to 0.99.
Homologues: Orthologues: macaque HERC2 (99% identical), rabbit HERC2 (97% identical), dog HERC2 (97% identical), rat Herc2 (96% identical), mouse Herc2 (96% identical), pig HERC2 (95% identical), guinea pig HERC2 (94% identical), tropical clawed frog herc2 (87% identical), zebrafish herc2 (83% identical), Drosophila melanogaster HERC2 (45% identical). Paralogues in human: HECTD4 (6% identical), HERC3 (6% identical), HERC4 (6% identical), HERC5 (6% identical), HERC6 (5% identical), HUWE1 (5% identical), HECW1 (5% identical), HECW2 (5% identical), HECTD1 (4% identical), TRIP12 (4% identical), UBE3A (4% identical), WWP1 (4% identical), and 12 more.
Diseases named in the same sentence as HERC2 in open-access papers:
HERC2 is named in the same sentence as 99 diseases in open-access papers, as found by Europe PMC text mining. Sharing a sentence is not in itself a finding about the gene and the disease. The quoted sentences say what the papers report.
Angelman syndrome (11 papers, 2009 to 2026). A neurogenetic disorder characterized by severe intellectual deficit and distinct facial dysmorphic features. "The HERC2 gene is located near an imprinting region of chromosome 15 associated with neurodevelopmental disorders like Angelman syndrome." (PMID 38570483, 2024). "Biallelic HERC2 variants associated with HERC2 Angelman-like syndrome include missense and frameshift mutations with a premature stop codon that result in a loss of function." (PMID 36241744, 2022). "Biallelic pathogenic sequence variants in the HERC2 gene are associated with HERC2 Angelman-like syndrome." (PMID 36241744, 2022). "More recently, a mutation in the HERC2 gene has been linked to the neurodevelopmental delay and dysfunction seen in Angelman syndrome and autism-spectrum disorders among the Amish community." (PMID 27528230, 2016). "A mutation in the HERC2 gene has been linked to a severe neurodevelopmental disorder with similarities to the Angelman syndrome." (PMID 27528230, 2016). "Biallelic hypomorphic variants in the E3 ubiquitin ligase HERC2 cause a neurodevelopmental disorder clinically resembling Angelman syndrome, characterized by global developmental delay, intellectual disability, autism spectrum features, and movement abnormalities." (PMID 41951624, 2026). "Together, these findings uncover a previously unknown role for HERC2 in autophagy regulation and provide insights into the pathomolecular mechanisms underlying the HERC2-related disorder and Angelman syndrome." (PMID 38570483, 2024). "Clinically, these findings may be relevant to cancer, as well as individuals with HERC2 Angelman-like syndrome due to biallelic HERC2 gene variants." (PMID 36241744, 2022). "To date, missense mutations in HERC2 have been associated with an autosomal recessive neurodevelopmental disorder with some phenotypical similarities to Angelman syndrome, and a homozygous deletion spanning HERC2 and OCA2 causing a more severe neurodevelopmental phenotype." (PMID 32571899, 2021). "For example, a neurodevelopmental delay featuring Angelman syndrome and autism spectrum disorder has been attributed to a homozygous missense mutation [NM_004667.5:c.1781C>T (p.Pro594Leu)] in the HERC2 gene or to a homozygous 286‐kb deletion between the contiguous genes HERC2 and OCA2 (chr15: g." (PMID 31665549, 2020). "HERC2 has been implicated in a human disorder with some features similar to Angelman syndrome." (PMID 27528230, 2016). "Therefore, we cannot discount the possibility that alterations in this pathway could be associated with clinical outcomes in HERC2 Angelman-like syndrome." (PMID 36241744, 2022). "However, more experiments are needed to confirm these hypotheses and to associate these mechanisms with clinical outcomes in HERC2 Angelman-like syndrome." (PMID 36241744, 2022). "Remarkably, the HERC2 gene is commonly deleted in individuals with Angelman syndrome, suggesting a potential contribution of HERC2 to the pathophysiology of this disease." (PMID 38570483, 2024). "Collectively, these observations show the important role of HERC2 in neurodevelopment and suggest a potential contribution of HERC2 to the pathophysiology of Angelman syndrome." (PMID 38570483, 2024). "Our investigation unveils a novel role for HERC2 as an autophagy regulator factor through the USP20-ULK1 axis, providing new insights into the pathomolecular basis of HERC2-related disorder and Angelman syndrome." (PMID 38570483, 2024). "For instance, FEM1B gain-of-function mutation, which cause a persistent activation of the reductive stress response, elicit developmental syndromes with some similarities to the HERC2 Angelman-like syndrome." (PMID 36241744, 2022). "Altogether, these findings identify the activation of C-RAF/MKK3/p38 signalling pathway in HERC2 Angelman-like syndrome and highlight the inhibition of RAF activity as a potential therapeutic option for individuals affected with these rare diseases." (PMID 36241744, 2022).
Angelman syndrome (continued). "The mutation of HERC2 found among the Old Order Amish with features similar to Angelman syndrome also suggests an important role for HERC2 in neurodevelopment." (PMID 27528230, 2016). "A decrease in HERC2 activities was also observed in human skin fibroblasts from individuals with an Angelman-like syndrome that express an unstable mutant protein of HERC2." (PMID 27528230, 2016). "Individuals from the Amish community with a punctual mutation in HERC2, HERC2P594L, suffer a developmental disorder with features similar to Angelman syndrome." (PMID 27528230, 2016). "Taking into account all the evidence presented in this study, it suggests that targeting USP20 and/or ULK1 could potentially hold therapeutic promise for individuals affected by HERC2-related disorder and Angelman syndrome." (PMID 38570483, 2024). "Notably, the HERC2 gene is commonly deleted in Angelman syndrome patients." (PMID 38570483, 2024). "In humans, the HERC2 genomic locus, including several partially duplicated paralogs (duplicons) of HERC2, corresponds to the chromosomal breakpoint region in deletions that cause the Prader-Willi and Angelman syndromes although lack of HERC2 protein does not seem to play a role in these syndromes." (PMID 20041218, 2009).
developmental delay (10 papers, 2016 to 2026). "For example, mutations in HERC2, which is a large E3 ubiquitin ligase with multiple structural domains, are linked to developmental delays and impairment caused by nervous system dysfunction." (PMID 40076702, 2025). "Several recessive mutations affecting the HERC2 gene cause developmental delay with Angelman-like features." (PMID 36241744, 2022). "Mutations in HERC2 were associated with developmental delay with Angelman-like features (including severe ID)." (PMID 34976023, 2021). "We suggest that HERC2 should be included in gene panels for non-specific severe neurodevelopmental disorders, in order to improve the sensitivity of diagnostic testing for patients with developmental delay but without a molecular diagnosis." (PMID 32571899, 2021). "The implication of HERC2 might not be surprising because of its implication in developmental delay, autism spectrum disorder, as well as Angelman‐like features." (PMID 31578829, 2020).
Intellectual disability (9 papers, 2019 to 2026). "Noteworthy genes such as GABA receptor subunits and HERC2, implicated in neurotransmission and intellectual disability, further add complexity to this genomic region." (PMID 38616334, 2024). "A missense mutation in HERC2 was associated with intellectual disability, autism, and gait disturbance." (PMID 37627046, 2023). "There was a homozygous pathogenic partial HERC2 gene deletion of exons 43–45 responsible for autosomal recessive HERC2-related disorder, which is characterized by intellectual disability, gait disturbance, seizures, hypotonia, and brain anomalies." (PMID 35663206, 2022). "After consolidating intellectual disability gene lists from two databases and one recent review article, we identified eight LRRK2 interacting proteins that have previously been linked to intellectual disability: ACTB, ACTG1, ATRX, DYNC1H1, HERC2, PPP2R1A, TUBA1A, and YWHAE." (PMID 31963867, 2020).
breast carcinoma (8 papers, 2019 to 2025). "LGSN, OCA2, and HERC2 reportedly mediated resistance to breast cancers." (PMID 36292733, 2022). "Mutations in HERC1 and HERC2 have been detected in leukemia cells (T-cell acute lymphoblastic leukemia (T-ALL) for HERC1 and T-cell prolymphocytic leukemia (T-PLL) for HERC1 and HERC2) and in breast cancer tumors." (PMID 31275856, 2019). "HERC2-mediated breast cancer gene 1 (BRCA1) degradation is involved in DNA double-strand breaks repair, thereby enhancing breast cancer cell proliferation." (PMID 36721234, 2023). "HERC1 is the founding member of the HERC family characterized in human breast cancer cells, followed by the identification of a total of six HERC members in human, which are phylogenetically divided into large HERCs (HERC1 and HERC2) and small HERCs (HERC3-6)." (PMID 36902023, 2023). "HERC2 can physically interact with TUSC4 in breast epithelial cells and breast carcinomas to promote BRCA1 stability." (PMID 35889210, 2022). "Other genes associating with this component were CHD3 in bladder cancer, HERC2 in ovary cancer, PIK3C2B in lung squamous cell cancer, EP300 in skin cancer (and breast cancer at a FDR of 2%), RBBP5 in pan-cancer, and SMC1B in pan-cancer." (PMID 35764656, 2022). "HERC2 ubiquitinates BRCA1 and expresses in breast epithelial cells, and breast carcinomas, indicating a function for HERC2 in breast carcinogenesis." (PMID 33113804, 2020). "Although the precise role of HERC2 in breast cancer pathogenesis has not yet been fully elucidated, it has been reported as a critical target for further investigation." (PMID 41300329, 2025).
melanoma (7 papers, 2011 to 2025). A malignant, usually aggressive tumor composed of atypical, neoplastic melanocytes. "Variants in TYR, TYRP1, CDKN2A, and HERC2 significantly contributed to risk, and light brown eye and hair colors were strongly associated with increased melanoma risk." (PMID 40429816, 2025). "The contribution of the other two markers, SLC45A2 rs16891982 (3.80%) and HERC2 rs1129038 (2.34%), indicated that they also have an important role in predicting melanoma risk." (PMID 33167923, 2020). "HERC2/OCA2 gene non-coding allele/haplotype in pigmented melanoma and amelanotic/hypomelanotic patients." (PMID 32966289, 2020). "A model of logistic regression including ancestry, melanoma risk factors and SNPs HERC2 rs1129038 and SLC24A5 rs1426654 in dominant models of inheritance showed significant associations with melanoma." (PMID 33167923, 2020). "Among the HERC2 variants (rs916977–intron 12, rs7170852–intron 56, and rs12913832–intron 86), only rs7170852 was associated with melanoma risk according to the homozygous dominant and recessive models (OR = 12.22, CI = 1.48–100.91, p < 0.0001; OR = 21.92, CI = 2.73–176.14, p < 0.0001, respectively)." (PMID 40429816, 2025). "However, even isolated HERC2 rs1129038 analysis shows that the AA genotype confers an increased risk for melanoma." (PMID 33167923, 2020). "We additionally investigated whether the association between PRS and melanoma was driven by the most significant SNP in the MDACC data set (rs12913832 in HERC2)." (PMID 24392023, 2013). "Some of the identified lead SNPs, mapping IRF4, HERC2, and TYR, were also found to be associated with melanoma or other skin diseases in the UKBiobank." (PMID 36672889, 2023). "According to these results, the best model for predicting melanoma development was the combination of the three factors (HERC2 rs1129038, SLC24A5 rs1426654, and SLC45A2 rs16891982)." (PMID 33167923, 2020). "to detect and characterize gene-gene interactions among HERC2 (rs1129038), SLC24A5 (rs1426654), and SLC45A2 (rs16891982) in risk of developing melanoma." (PMID 33167923, 2020). "In contrast, the MC1R (chromosome 16) and HERC2/OCA2 (chromosome 15) loci, both of which affect pigmentation, lose their significance, implying that they influence melanoma risk through their effects on pigmentation phenotypes." (PMID 28973033, 2017). "The association of HERC2/OCA2 and CKDN2A/MTAP loci with melanoma risk were confirmed in subsequent meta-analyses." (PMID 28973033, 2017). "In the haplotype analysis of OCA2 (rs7497270, rs1800401, rs1800407, and rs1800414) and HERC2 (rs916977, rs7170852, and rs12913832), we observed that the TCCTTTA haplotype in males was associated with a protective effect against melanoma (OR = 0.14, 95% CI = 0.02–0.96)." (PMID 40429816, 2025). "The combination of SLC24A5 rs1426654AA and SLC45A2 rs16891982GG was significantly associated with melanoma risk regardless of the genotype of HERC2 rs1129038, confirming the lower weight of HERC2 (2.34%) in the analysis of gene interaction." (PMID 33167923, 2020). "Common noncoding polymorphisms in the HERC2/OCA2 locus have previously been associated with melanoma, with both HERC2 rs12913832 and OCA2 intron haplotype region SNPs associated with eye color and melanoma." (PMID 32966289, 2020). "Thus, SNPs HERC2 rs1129038 and SLC24A5 rs1426654 remained strongly associated with risk for the development of melanoma in a dominant model." (PMID 33167923, 2020). "Interaction of HERC2/OCA2 rs12913832 and rs7174027 in blue eye colour, sun sensitivity and amelanotic/hypomelanotic melanoma." (PMID 32966289, 2020). "Recent GWAS have unveiled association between SNPs or genetic variants in MC1R, TPCN2, ASIP, KITLG, SLC24A5, TYR, IRF4, OCA2/HERC2, SLC24A4, SLC45A2, TYRP1, and pigmentation as well as melanoma." (PMID 21559390, 2011).
skin cancer (6 papers, 2019 to 2023). "We found HERC2-d predictable in HMF skin cancer patients (biallelic: PR-AUC-E = 0.24, AUROC = 0.73; monoallelic: PR-AUC-E = 0.23, AUROC = 0.66), primarily based on enrichment of deletions in non-microhomologous and non-repetitive regions." (PMID 36883553, 2023). "Moreover, variants at the HERC2/OCA2 locus have been associated with pigmentation phenotypes and the risk of developing several types of skin cancer." (PMID 36980718, 2023). "We further found that inclusion of monoallelic LOF events matched the predictive power for ATRX biallelic LOF in CNS cancers and HERC2 biallelic LOF in skin cancers, suggesting that single genetic hits are sufficient to affect repair and ensuing mutational patterns for these genes." (PMID 36883553, 2023). "BNC2, HERC2, OCA2, RALY, and TYR are pleiotropic for Category B Phenotypes (skin colour phenotypes) and Category C Phenotypes (skin cancer phenotypes)." (PMID 35907981, 2022).
autism (5 papers, 2018 to 2026). Persistent deficits in social interaction and communication and interaction as well as a markedly restricted repertoire of activity and interest as well as repetitive patterns of behavior. "HERC2 interacts with the autism-linked ubiquitin ligase RNF8/UBC13 and the scaffold protein NEURL4, taking part in a novel cytoplasmic ubiquitin-signalling network that suppresses synapse formation in the brain." (PMID 37307281, 2023).
colorectal cancer (5 papers, 2019 to 2026). A primary or metastatic malignant neoplasm that affects the colon or rectum. "In this context, mutations in HERC2 have been detected in T‐cell prolymphocytic leukemia and in gastric and colorectal carcinomas with microsatellite instability." (PMID 31665549, 2020). "Mutations in HERC2 have also been described in leukemia, and gastric and colorectal carcinomas [NM_004667.5:c.541delA (p.Ser181ValfsX85)]." (PMID 31665549, 2020). "Frameshift mutations of HERC2 have been reported in gastric and colorectal cancer with microsatellite instability." (PMID 30744164, 2019). "AIMs, rs12916300 and rs12913832, mapped to HERC2 (chr15) and rs694339 in the CBLN2 (chr18) genes were associated with colorectal cancer risk in a European sample." (PMID 36911410, 2023).
autism spectrum disorder (4 papers, 2016 to 2021). A spectrum of developmental disorders that includes autism, and Asperger syndrome. "More recently, a mutation in the HERC2 gene has been linked to neurodevelopmental delay and dysfunction in both AS and autism-spectrum disorders among the Old Order Amish." (PMID 27528230, 2016).
uveal melanoma (4 papers, 2020 to 2026). A melanoma derived from melanocytes of the uveal tract. "Single nucleotide polymorphisms (SNPs) in IRF4 and HERC2 are associated with risk for disomy or monosomy of chromosome 3 (D3 or M3) uveal melanoma (UM), respectively." (PMID 41377059, 2026). "Interestingly, both rs12203592 in IRF4 and rs12913832 in HERC2, the two most important genetic determinants of iris freckles and nevi found in this work, have also been recently identified as risk factors for developing uveal melanoma." (PMID 40261663, 2025). "Moreover, the HERC2 locus has been associated with cutaneous melanoma and uveal melanoma." (PMID 31665549, 2020).